DCBLD1 (discoidin, CUB and LCCL domain containing 1)
Diseases named in the same sentence as DCBLD1 in open-access papers (continued):
Sharing a sentence is not in itself a finding about the gene and the disease.
tumor (7 papers, 2011 to 2026). "Bioluminescence images revealed that tumor xenografts grew remarkably larger in the DCBLD1 OE group than in the EV group." (PMID 41522352, 2026). "Quantitative assessment revealed markedly reduced tumor burden in DCBLD1-/- mice relative to WT counterparts." (PMID 41522352, 2026). "Concurrently, in the PDXs model, DCBLD1 knockdown led to a marked decrease in tumor weight and tumor volume, demonstrating the efficacy of DCBLD1 inhibition in vivo." (PMID 41522352, 2026). "In the PDOs model, DCBLD1 knockdown resulted in a significant reduction in organoid number and size, suggesting impaired tumor growth and survival ex vivo." (PMID 41522352, 2026). "We stratified the TCGA-LUAD dataset based on EGFR mutation status and observed significantly elevated DCBLD1 expression in both EGFR WT and EGFR Mut LUAD tissues compared to adjacent non-tumor tissues." (PMID 41522352, 2026). "We found that L-lactate, one of the most abundant metabolites in the tumor microenvironment generated through glycolysis, induced time-dependent upregulation in the mRNA expression of DCBLD1." (PMID 38291438, 2024). "The SCNA module compares tumor infiltration relationships among tumors with different somatic copy number variations for DCBLD1." (PMID 35844572, 2022). "For the first time, this study reported the effects of the DCBLD1 gene on the tumor microenvironment and prognosis in HNSC." (PMID 35844572, 2022). "On the other hand, we also showed that DCBLD1 expression is higher in tumor tissue for all four cancers." (PMID 34140574, 2021). "The tumor growth was significantly reduced after suppressing the expression of DCBLD1 and cell proliferation marker Ki-67 was significantly decreased after suppressing the expression of DCBLD1." (PMID 32231272, 2020). "These collective findings led us to hypothesize that DCBLD1 promotes tumor growth through EGFR signaling modulation." (PMID 41522352, 2026). "Additionally, we examined the expression of proliferating cell nuclear antigen (PCNA) in DCBLD1-OV and DCBLD1-KD tumor tissues generated from HeLa cells using IHC." (PMID 38291438, 2024). "In contrast, DCBLD1 overexpression substantially amplified tumor volume." (PMID 38291438, 2024). "This suggests the important role of DCBLD1 in tumor progression and migration." (PMID 35844572, 2022). "DCBLD1 behaved like an oncogene, promoting tumor growth by influencing cell cycle progression." (PMID 32231272, 2020). "In vivo experiments also showed that downregulation of DCBLD1 inhibited tumor growth." (PMID 32231272, 2020). "This analysis revealed significantly elevated DCBLD1 expression in both EGFR WT and EGFR Mut LUAD tissues compared to adjacent non-tumor tissues." (PMID 41522352, 2026). "Following IHC confirmation of DCBLD1 overexpression in two cases (Case 1: EGFR WT; Case 2: EGFR Mut, exon 19 deletion), tumor tissues were used to establish both PDO and PDX models." (PMID 41522352, 2026). "This is consistent with observation that both LMP tumours harbor allelic imbalance of the chr6q arm which include the ROS1, DCBLD1, and GOPC loci." (PMID 22163003, 2011). "Although tumor growth was partially limited by GEF in DCBLD1 OE mice, this tendency towards increased growth was not reversed." (PMID 41522352, 2026). "However, there are no relevant studies about the role of DCBLD1 in the tumor microenvironment and prognosis in HNSCC." (PMID 35844572, 2022).
cancer (6 papers, 2020 to 2026). A tumor composed of atypical neoplastic, often pleomorphic cells that invade other tissues. "Normal cervical tissues bore a low level of DCBLD1, whereas Cancer tissues exhibited significantly higher signals." (PMID 38291438, 2024). "Subsequently, HNSCC was focused, and a higher expression of DCBLD1 was demonstrated in cancer tissues than in normal tissues (p < 0.001)." (PMID 35844572, 2022). "Although multiple studies have now described SNPs in the DCBLD1 promoter region in different oncology contexts, the role of DCBLD1 itself in cancer and its function in both normal and oncology settings remain poorly understood." (PMID 34140574, 2021). "Evaluating the common changes in those three cancers for DCBLD1 high cases will allow to better understand DCBLD1 role in oncology and to further clarify how DCBLD1 is associated with the integrin signaling pathway." (PMID 34140574, 2021). "In this study, we showed that basal-like cancers had a high expression of DCBLD1 in comparison to other subtypes." (PMID 34140574, 2021). "Moreover, elevated DCBLD1 expression correlates with unfavorable prognoses across multiple cancer types, including NSCLC, breast cancer, and head and neck squamous cell carcinoma 9,10." (PMID 41522352, 2026). "DCBLD1 is highly expressed in several kinds of cancer and plays a potential prognostic factor." (PMID 35844572, 2022). "We determined the differential expression of DCBLD1 in pan-cancer and HNSCC from 546 patients." (PMID 35844572, 2022). "Identifying how DCBLD1 gene expression is regulated might help understand why it has a prognostic value in some cancers." (PMID 34140574, 2021). "The Discoidin, CUB, and LCCL domain-containing protein (DCBLD) family consists of two type-I transmembrane scaffolding receptors, DCBLD1 and DCBLD2, which play important roles in development and cancer." (PMID 32606017, 2020). "The plasma membrane receptors DCBLD1 and DCBLD2 modulate basic cellular processes that are fundamental to vertebrate development, glucose homeostasis, and the progression of certain cancers." (PMID 32606017, 2020). "The fact that DCBLD1 was upregulated also in cancers for which it has no prognostic value suggests that factors regulating DCBLD1 might be generally regulated in cancer." (PMID 34140574, 2021).
adenocarcinoma (2 papers, 2020 to 2026). A common cancer characterized by the presence of malignant glandular cells. "H&E staining of lungs demonstrated that minimal alveolar lesions in DCBLD1-/- mice, whereas WT mice developed extensive adenocarcinomas." (PMID 41522352, 2026).
carcinomas of the (1 paper, 2024). "We used immunohistochemistry (IHC) to probe the presence of DCBLD1 in a large collection of normal, carcinomas of the cervix." (PMID 38291438, 2024).
infection (1 paper, 2024). The state of being infected such as from the introduction of a foreign agent such as serum, vaccine, antigenic substance or organism. "In contrast to APOE, DCBLD1 was significantly downregulated in acute death cases compared to both normal and long infection cases during SARS-CoV-2 infection." (PMID 38752789, 2024).
DCBLD1 also shares sentences with these, for which no sentence is quoted: colorectal tumors (1 paper); lung squamous cell carcinoma (1); non-small cell lung carcinoma (1); prostate adenocarcinoma (1); prostate carcinoma (1); small cell lung carcinoma (1); squamous cell carcinoma (1).